DPP4 (dipeptidyl peptidase 4)
Diseases named in the same sentence as DPP4 in open-access papers (continued):
Sharing a sentence is not in itself a finding about the gene and the disease.
gastro-esophageal reflux (1 paper, 2011). "The results support the deduction that BE is a tissue with enhanced glycoprotein synthesis machinery (DPP4, ATP2A3, AGR2) designed to provide strong mucosal defenses aimed at resisting gastro-esophageal reflux." (PMID 21829465, 2011).
H1N1 influenza (1 paper, 2020). "The invasion-mechanism of SARS-CoV-2 and SARS-CoV, involves binding of its spike protein with angiotensin-converting enzyme 2 (ACE2) receptors; MERS-CoV utilizes dipeptidyl peptidase 4 (DPP4), whereas H1N1 influenza is equipped with hemagglutinin protein." (PMID 33333995, 2020).
hemorrhoid (1 paper, 2022). Dilated veins in the anal canal. "Still, at present, it is difficult to understand the differences seen in the hemorrhoids and diverticula groups, where sCD26 but not DPP4 levels were shown for the first time to be statistically different, with lower levels in women with hemorrhoids and in men with diverticula." (PMID 36230486, 2022). "Curiously, when the analysis was performed by sex, only sCD26 levels (but not DPP4) were statistically different in men with diverticula (mainly) and NAA, whereas in women, differences were only found in the hemorrhoids group." (PMID 36230486, 2022).
Hepatitis B (1 paper, 2023). "For example, for Hepatitis B, predicted gene #2, F5; predicted gene #6, DECR1; predicted gene #7, SLC27A5, and predicted gene #9, DPP4, are all associated with liver function by the GeneCards platform." (PMID 36791052, 2023).
Hernia (1 paper, 2025). "In a translational approach, we compared the DPP4 activity in serum from 34 infants with confirmed BA, obtained at the time of KPE, with the DPP4 activity in serum from 14 immunologically healthy infants who underwent routine surgery (e.g. hernia repair)." (PMID 40825831, 2025).
hyperlipemia (1 paper, 2015). "In sum, the DPP4 inhibition in cows did not affect glycaemic control like it is shown in humans, but was able to impact hyperlipemia, as NEFA and TG decreased." (PMID 26291537, 2015).
hypersensitivity reactions (1 paper, 2025). "In postmarketing reports, DPP-4 inhibitors have also been associated with hypersensitivity reactions, including anaphylaxis and angioedema, and are therefore contraindicated in patients with a history of hypersensitivity reactions." (PMID 41012462, 2025).
hypertensive heart disease (1 paper, 2019). Abnormal enlargement of the heart resulting from long-standing hypertension. "In this study, we tested the effects of selective DPP4 inhibition on the progression of renal disease in a nondiabetic model of hypertensive heart disease." (PMID 30774748, 2019). "In this study, we tested the effects of selective DPP4 inhibition on the progression of renal disease in a nondiabetic model of hypertensive heart disease using Dahl salt-sensitive rats." (PMID 30774748, 2019).
Immunodeficiency (1 paper, 2021). Failure of the immune system to protect the body adequately from infection, due to the absence or insufficiency of some component process or substance. "Notably, serum or plasma levels of sCD26/DPP4 protein and enzymatic activity are meanwhile regarded as indicators for immunodeficiency and/or increased lymphocyte activity in inflammation or cancer, respectively." (PMID 35003134, 2021). "Thus, it was recently demonstrated by Casrouge and co-workers that individuals with congenital lymphocyte-immunodeficiency displayed decreased sCD26/DPP4 serum levels that were normalized upon restoration of hematopoiesis." (PMID 35003134, 2021).
invasive breast ductal carcinoma (1 paper, 2022). "FAP is found to form a protease complex with dipeptidyl peptidase IV (DPP4), which is another type II transmembrane protein with serine protease activity, at the endothelial cells of capillary-like micro-vessels within invasive breast ductal carcinoma." (PMID 35222418, 2022).
leishmaniasis (1 paper, 2025). Infectious disease that is transmitted through the bite of hematophagous female phlebotomine sand flies. "Moreover, dipeptidyl peptidase-4 (Dpp4) upregulation also exacerbates the reduced capacity of anti-TNF immunosuppressed mice to eliminate the infection, as its increased presence has been observed in unresolved cases of leishmaniasis compared to levels in cured patients and controls." (PMID 40808943, 2025).
leukoplakia (1 paper, 2024). A white patch or plaque on a mucous membrane that cannot be characterized clinically or pathologically as any other disease. "Furthermore, leukoplakia is well known to have higher malignant transformation than OLP which was notably reflected on its higher DPP-4 levels than in OLP." (PMID 39390508, 2024).
limb ischemia (1 paper, 2013). A ischemia that involves the limb. "Third, since the BM and circulatory concentrations of other functionally homologous members of the DPP family were not studied, their possible compensatory roles in the setting of limb ischemia in DPP4-deficinent rats remain to be elucidated." (PMID 23517567, 2013).
macular edema (1 paper, 2016). "Currently, there is no definite evidence that DPP4-inhibitors cause macular edema or neovascularization in the human retina." (PMID 27381080, 2016).
mastocytosis (1 paper, 2019). A clonal myeloproliferative neoplasm characterized by the proliferation and accumulation of neoplastic mast cells in one or multiple organs or organ systems. "The study revealed that two proteins, neural cell adhesion molecule L1 (L1CAM/CD171) and dipeptidyl peptidase 4 (DDP4/CD26), served as the novel biomarkers for human skin mast cells in normal, psoriatic, and mastocytosis skin." (PMID 30845706, 2019).
morphine dependence (1 paper, 2022). Strong dependence, both physiological and emotional, upon morphine. "Thus, the purpose of the present study was to examine the effect of the selective dipeptidyl peptidase-4 (DPP-4) inhibitor, linagliptin, on morphine dependence in mice." (PMID 35458676, 2022).
mucinous ovarian cancer (1 paper, 2026). An invasive malignant neoplasm that arises from the ovary and is characterized by the presence of malignant epithelial cells that contain intracytoplasmic mucin and may resemble the epithelial cells of the endocervix or gastrointestinal tract. "We then performed cis drug-target MR for PPARG, DPP4, ABCC8/KCNJ11, and SLC5A2, integrated triangulation, colocalization, and mediation analyses, and experimentally interrogated the prioritized PPARG/ABCC8-KCNJ11-lactate-invasive mucinous ovarian cancer (IMOC) triangle." (PMID 42278567, 2026).
mucositis (1 paper, 2019). Mucositis is inflammation and damage of the mucous membranes lining the mouth and other parts of the gastrointestinal (GI) tract. "In this study, we revealed that DPP-4 inhibitors showed a significant improvement on mice models of 5-FU induced mucositis in diarrhea score, histologic findings, and TNF- α expression." (PMID 31664952, 2019). "Interestingly, we revealed that DPP-4 inhibitors showed a significant improvement on mice models of 5-FU induced mucositis in diarrhea score, histologic findings, and TNF- α expression." (PMID 31664952, 2019). "In addition, we suggest that the DPP-4 inhibitors play a role in attenuating the severity of mucositis in the TNF-α dependent pathway, as the TNF-α expression is significantly down-regulated in the DPP-4i + 5-FU group." (PMID 31664952, 2019). "However, there was only a few studies that have examined a role of DPP-4 inhibitor in mucositis." (PMID 31664952, 2019). "Therefore, we assumed that the DPP-4 inhibitor via the GLP-1 dependent pathway might also have an important role in healing mucositis." (PMID 31664952, 2019). "However, there was only a few studies providing evidence of a role of DPP-4 inhibitor in mucositis." (PMID 31664952, 2019).
mycobacterial pulmonary infection (1 paper, 2025). "Among the treatments for type 2 DM, metformin reportedly has a protective effect against TB incidence, whereas dipeptidyl peptidase-4 (DPP-4) inhibitors have a neutral role in mycobacterial pulmonary infection." (PMID 41250123, 2025).
Nausea (1 paper, 2012). A sensation of unease in the stomach together with an urge to vomit. "This can be compared with DPP-4 inhibitors such as sitagliptin and saxagliptin which have nausea incidence rates of 1-2% and 2–4%, respectively, close to those achieved with placebo." (PMID 23125920, 2012).
nephrotoxicity (1 paper, 2021). Toxicity that causes injury to the kidney or damages its function. "Although DPP-4 activity did not increase in the kidneys of mice with induced cyclosporine nephrotoxicity, DA-1229 treatment significantly suppressed DPP-4 activity in both plasma and renal tissues." (PMID 33803842, 2021).
ocular hypertension (1 paper, 2016). Abnormally high intraocular pressure. "A reduction in DPP4 activity with Dex treatment is consistent with the resulting ECM dysregulation and accumulation in the TM of patients with steroid induced ocular hypertension." (PMID 27783649, 2016).
oral squamous cell carcinoma (1 paper, 2024). "Our current findings regarding oral squamous cell carcinoma (OSCC) highlight the anti-oncogenic role of DPP-4." (PMID 39390508, 2024).
osteitis (1 paper, 2024). "A 57-year-old female patient with an 8-year history of T2DM, treated with metformin, SGLT2i, and dipeptidyl-peptidase 4 inhibitor, with a history of a panaritium on the third finger of her left hand, complicated by osteitis that required distal phalanx amputation in July 2022." (PMID 39202075, 2024).
ovarian dysfunction (1 paper, 2020). The inability of the ovaries to function. "In non-pregnant poor responders who were given sitagliptin, a dipeptidyl peptidase-4 (DPP-4) inhibitor, and underwent ART, ovarian dysfunction was ameliorated, and ongoing pregnancy rates increased significantly, in those patients whose serum TAGE levels were decreased by the sitagliptin." (PMID 33292465, 2020).
ovarian tumours (1 paper, 2021). "DPP4 protein expression and activity were measured in serum and in ovarian tumour tissue." (PMID 33513866, 2021).
overnutrition (1 paper, 2018). An imbalanced nutritional status resulting from excessive intake of nutrients. "The aim of the study was to determine whether a 12-week treatment with DPP-4 inhibitor SIT ameliorates overnutrition-induced progression of abnormal cardiac dysfunction and glucose homeostasis in obese female mice." (PMID 30116740, 2018). "DPP-4 activity and GLP-1 levels will be also needed to be measured to confirm that chronic overnutrition elevates plasma DPP-4 activity and DPP-4 inhibitor inhibits plasma DPP-4 activity." (PMID 30116740, 2018).
prion disease (1 paper, 2023). A transmissible disease that is caused by a protein that is able to induce abnormal folding of normal cellular proteins, leading to characteristic spongiform brain changes, which are associated with neuronal loss without an inflammatory response. "In this regard, it is notable that inflammation up-regulates astrocytic DPP4 expression and that conversion of astrocytes to a neuroinflammatory or “reactive” phenotype appears to be an important early step in prion disease pathogenesis." (PMID 36574660, 2023). "By applying inhibitors of these proteins to prion-infected cells, we also show that the β-cleavage activity of dipeptidyl peptidase-4 in particular may be important in the pathogenesis of prion diseases." (PMID 36574660, 2023). "Returning to the prion disease context, since DPP4-mediated β-cleavage of PrPC seems to promote PrPSc accumulation in primary cerebellar glial cultures, brain-penetrant DPP4 inhibitors could be tested in animal models of prion infections." (PMID 36574660, 2023). "In contrast to DPP4, FAP may act as a tissue-specific regulator of PrPC β-cleavage outside of a prion disease context, perhaps affecting the physiological function of PrPC." (PMID 36574660, 2023).
pulmonary embolism (1 paper, 2025). The obstruction of the pulmonary artery or one of its branches by an embolus, sometimes associated with infarction of the lung. "DPP-4 inhibitors did not demonstrate significant associations with respiratory outcomes overall, although individual agents such as linagliptin showed possible protective effects against pulmonary embolism in subgroup analyses." (PMID 41567683, 2025).
retinal detachment (1 paper, 2024). An eye emergency condition which may lead to blindness if left untreated. "The increase in DPP4 during retinal detachment thus depresses glucose metabolism in retinal cells." (PMID 38397833, 2024).
retinopathy of prematurity (1 paper, 2016). A bilateral retinopathy characterized by neovascularization, scarring, retinal detachment, and eventually blindness. "We tested the in-vivo effects of DPP4-inhibitor on retinal vascular permeability, using a retinopathy of prematurity mouse model." (PMID 27381080, 2016). "In the model of retinopathy of prematurity, DPP4-inhibitor increased not only retinal vascularity but also leakage." (PMID 27381080, 2016).
skin aging (1 paper, 2025). The gradual irreversible changes in structure of skin that occur as a result of the passage of time.. "Various experimental ADC platforms have been developed to identify senescence-associated markers, including uPAR, DPP4 (CD26), and ApoD, with applications spanning skin aging to fibrotic disorders." (PMID 40507795, 2025).
small cell lung carcinoma (1 paper, 2021). Small cell lung cancer (SCLC) is a highly aggressive malignant neoplasm, accounting for 10-15% of lung cancer cases, characterized byrapid growth, and early metastasis. "In small cell lung cancer, DPP-4 levels were significantly diminished; however, restoration of DPP-4 induced apoptosis and cell cycle arrest via the p21 accumulation, and suppressed tumor growth and metastasis." (PMID 34063285, 2021).
spinocerebellar ataxia type 1 (1 paper, 2021). Spinocerebellar ataxia type 1 (SCA1) is a subtype of type I autosomal dominant cerebellar ataxia (ADCA type I) characterized by dysarthria, writing difficulties, limb ataxia, and commonly nystagmus and saccadic abnormalities. "Papillary variants express platelet derived growth factor receptor (PDGFR-α)- alpha and dipeptidyl peptidase-4 (DPP4) as markers, whereas reticular cells express PDGFR-α, delta-like noncanonical Notch ligand 1(DLK1) and spinocerebellar ataxia type 1 (SCA1)." (PMID 34063059, 2021).
streptococcal infection (1 paper, 2020). Any of the several infectious disorders caused by members of streptococcus, a genus of gram positive bacteria belonging to the family Streptococcaceae. "The only hypothesis about the origin of anti-CD26 autoantibodies in healthy controls links again CD26/DPP4 with plasminogen as a consequence of an abnormal immune stimulation triggered by streptokinase (SK) released during streptococcal infections, a mechanism that also produces antiplasminogen." (PMID 32051696, 2020).
synovitis (1 paper, 2025). Inflammation of a synovial membrane. "Cases of remitting seronegative symmetrical synovitis with pitting edema syndrome, presenting as symmetrical synovitis with dorsal hand and foot edema, have also been reported in individuals receiving DPP-4 inhibitors." (PMID 40607140, 2025).
tauopathy (1 paper, 2019). Neurodegenerative disorders involving deposition of abnormal tau protein isoforms (tau proteins) in neurons and glial cells in the brain. "In this study, we examined whether the DPP-4 inhibitor linagliptin affects tau pathology and cognition in a mouse model of tauopathy (PS19) challenged with HFD." (PMID 31126115, 2019). "No studies have previously examined how DPP-4 inhibitors affect tau pathology and memory deficits in tauopathy models." (PMID 31126115, 2019). "So far, no consensus has been made regarding the effects of DPP-4 inhibition on tauopathy-specific pathology and related cognitive dysfunction independent of amyloid pathology." (PMID 31126115, 2019).
thyroid-associated ophthalmopathy (1 paper, 2023). "In addition, the ELISA results indicated that protein expression levels of DPP4 were ­significantly upregulated in thyroid-associated ophthalmopathy (TAO) patients compared with healthy controls." (PMID 37350750, 2023).
Tinnitus (1 paper, 2025). Tinnitus is an auditory perception that can be described as the experience of sound, in the ear or in the head, in the absence of external acoustic stimulation. "The SGLT2 and DPP4 cohorts were compared for tinnitus incidence using Kaplan–Meier analysis and multivariable Cox regression." (PMID 40863028, 2025).
type 1 diabetic nephropathy (1 paper, 2015). "We wanted to demonstrate that linagliptin reduces high glucose induced interaction between membrane bound DPP4 and CIM6PR in vitro and demonstrate reduction in active TGFß mediated downstream effects in a rodent model of type 1 diabetic nephropathy independent of high glycaemic levels." (PMID 26509887, 2015).
uremia (1 paper, 2011). A clinical syndrome associated with the retention of renal waste products or uremic toxins in the blood. "DPP-4 inhibition increases plasma GLP-1 levels, particularly in uremia, and reduces expression of cardiac mRNA levels of matrix proteins and B-type natriuretic peptides (BNP)." (PMID 22125632, 2011). "The results showed that DPP-4 inhibition increases plasma GLP-1 levels, particularly in uremia, suggesting that linagliptin may offer a unique approach for treating uremic cardiomyopathy in CKD patients." (PMID 22125632, 2011). "This is the first study showing that the DPP-4 inhibitor, linagliptin, may exert positive effects on CHF in the setting of uremia." (PMID 22125632, 2011).
villous adenoma (1 paper, 2020). An epithelial neoplasm morphologically characterized by the presence of a villous architectural pattern. "On the contrary, the group with tubulovillous/villous adenomas exhibited higher titres of anti-CD26 (statistically significant for the IgG isotype, the one independent of sex and age) together with high levels of DPP4 and low levels of sCD26." (PMID 32051696, 2020).
vitamin D deficiency (1 paper, 2021). A nutritional condition produced by a deficiency of VITAMIN D in the diet, insufficient production of vitamin D in the skin, inadequate absorption of vitamin D from the diet, or abnormal conversion of vitamin D to its bioactive metabolites. "In this context, vitamin D deficiency has been shown to remarkably reduce the expression of the DPP4/CD26 receptor in vivo." (PMID 34684369, 2021).
Werner syndrome (1 paper, 2020). "The effectiveness of the DPP-4 inhibitor, sitagliptin, for a pioglitazone non-responder patient with Werner syndrome has been reported." (PMID 33373317, 2020).
α-synucleinopathies (1 paper, 2026). "Emerging therapies involving gut peptides, such as GLP-1 analogs and DPP-4 inhibitors, show promise, especially in patients with α-synucleinopathies." (PMID 41918339, 2026).